BAP1 (BRCA1 associated deubiquitinase 1)
Diseases named in the same sentence as BAP1 in open-access papers (continued):
Sharing a sentence is not in itself a finding about the gene and the disease.
tumor (continued). "The diversity of tumor-infiltrating immune cells can be determined by the tumor phenotype and aberrations in the BAP1 gene." (PMID 36012262, 2022). "This association does not seem to be related to differences in patient age, sex, tumor diameter, tumor thickness, BAP-1 expression, AJCC T-category, to the quantity of sunlight or UV, to temperature, or to differences in wealth." (PMID 36310339, 2022). "Together, our study demonstrates that KEAP1 deubiquitination by BAP1 is novel tumor suppressive mechanism of LUAD." (PMID 35052618, 2022). "It was certified that BAP1 mutation evoked augmented expression of C-C chemokine receptor 5 (CCR5) on Tregs and tumor cells." (PMID 36052158, 2022). "Concordance was high between PDX models and paired tumor samples for expression of key markers of interest (BAP1, WT1, mesothelin, PD-L1 and VISTA) and genomic alterations." (PMID 36380343, 2022). "The BAP1 gene, which encodes BRCA1-associated protein 1 (BAP1), is located on chromosome 3 and has tumor suppressor activity." (PMID 35804863, 2022). "For a tumor to be classified as BAP-1 positive, at least 33% of tumor cell nuclei had to be positively stained, and accumulation of chromogen in nucleoli or similar did not suffice." (PMID 36310339, 2022). "It is also suggested that BAP1, SETD2, and PBRM1 are prevalent co-drivers of tumor grade and invasion of ccRCC and associated with aggressive progression." (PMID 35979371, 2022). "Of note, our NGS and IHC results on the patient’s LUAD tissue also suggest a possible functional role of BAP1 in this tumor, albeit at a later stage of tumor progression." (PMID 35885614, 2022). "The BAP-1 mutation in this population poses a high risk of developing MPM and other neoplasms in individuals and affected families." (PMID 36553016, 2022). "Next, we investigated tumor cell migration in an inducible BAP1 KO model in which BAP1 was deleted after cells were injected into yolk sac." (PMID 34706158, 2022). "According to the statistical evaluation, measuring the mRNA level of BAP1 is suitable for distinguishing ccRCC tumour specimens from normal kidney tissues with only an 8 per cent false rate (in 99% CI) (green line)." (PMID 35586183, 2022). "There is evidence that BAP1 mutated UM tumors can be targeted through poly [ADP-ribose] polymerase (PARP) inhibition, albeit indirectly and in BAP1 loss tumor cell lines." (PMID 36292588, 2022). "RCC with BAP1 mutation has significant morphological overlap with Xp11 translocation RCC and is also associated with a higher tumor stage." (PMID 36591111, 2022). "BAP1 loss displayed the ability to increase the sensitivity of cancer cells also to BET inhibitors, which remarkably result in potent anti-tumor effects in CCA models, especially in combination with PARPi." (PMID 35563769, 2022). "BAP1 is a multifunctional tumor suppressor involved in chromatin remodeling, DNA damage repair, cell cycle control, regulated cell death, and the immune response." (PMID 34976173, 2022). "Tumor DNA from a cohort of 100 UM patients from Moorfields Biobank (UK) that had undergone enucleation were sequenced for known UM driver genes (BAP1, SF3B1, EIF1AX, GNAQ, and GNA11)." (PMID 36077643, 2022).
tumor (continued). "These primary mutation events contribute to tumor initiation while subsequence mutations in other genes, such as BAP1, SF3B1, and EIF1AX, contribute to tumor progression and metastasis." (PMID 34706158, 2022). "Overall, our findings stress the importance of an appropriate surveillance program for BAP1-TPDS carriers, which should involve not only those individuals who have already developed a tumor but also their healthy relatives carrying a BAP1 PV." (PMID 35885614, 2022). "It has been found that PBRM1 modulates HIF1a-VEGF signal and STAT3-Interferon signal and BAP1 promotes genomic instability and therefore accelerates tumor metastasis." (PMID 35439951, 2022). "Ninety tumors were successfully subjected to immunohistochemical analyss: Tumor sections were labeled with an antibody to BAP1, and protein abundance and cellular localization were determined." (PMID 36077643, 2022). "BAP1 is another tumor suppressor repressing SLC7A11 transcription through H2A histone ubiquitination, which inhibits cystine uptake and GSH biosynthesis, and promotes ferroptosis." (PMID 36552652, 2022). "The UM92.1 cells were acquired from a large tumor mass that had destroyed the eye and orbit and led to metastases, although this tumor had disomy of chromosome 3 and expressed BAP1." (PMID 35740554, 2022). "To confirm the BAP1-dependent tumor growth in vivo, we depleted BAP1 in mouse SCLC KP1 cells by CRISPR and determined the cell growth both in vitro and in vivo." (PMID 35194152, 2022). "In this section, we review articles that develop radiogenomic models to predict tumor gene mutational profile in ccRCC, which mostly focused on the previously discussed PBRM1 and BAP1 mutations." (PMID 35565216, 2022). "However, atypical stroma cells in biphasic MPM can exhibit nuclear expression of BAP1 as well while epithelioid tumor cells stain negatively, posing a diagnostic challenge to distinguish atypical stromal cells from neoplastic cells and categorize the tumor accordingly." (PMID 35205798, 2022). "To carry out such a multilevel investigation, we measured the mRNA levels of VHL, SETD2, PBRM1 and BAP1 genes by qPCR on the same tumour-normal paired sample set used for our CNV characterisation." (PMID 35586183, 2022). "Our results demonstrate that BAP1 is a tumor suppressor, which suppresses NRF2 in LUAD by deubiquitinating KEAP1." (PMID 35052618, 2022). "Cancer-associated BAP1 mutants lose their abilities to repress SLC7A11, leading to attenuation of ferroptosis and tumor promotion." (PMID 34830866, 2021). "For tumors with IHC stains, we used retained BAP1 expression in 33% of tumor cells as a cutoff, in accordance with previous publications." (PMID 33903674, 2021). "We show here that single‐pattern cytoplasmic BAP1 staining is associated with lower BAP1 gene expression, epithelial‐like EMT markers, epithelioid tumor histology, and longer patient survival." (PMID 32944962, 2021). "BAP1 functions as a major tumor suppressor that mediates DNA damage repair, cell-cycle control, chromatin modification, programmed cell death, and the immune response." (PMID 34439859, 2021). "BAP1 is also involved in the epigenetic regulation of many genes via polycomb repressor complex 2 (PRC2), which has potential therapeutic relevance, as the loss of BAP1 promotes sensitivity to PRC2 inhibitors, which block tumour growth and invasion." (PMID 34226685, 2021). "All tissues examined showed strong BAP1 and H3K27me3 nuclear staining in the majority of tumor cells (3+ in >67%)." (PMID 34277422, 2021). "BAP1, a tumor suppressor, is involved in the DNA repair machinery, regulation of cell death, and metabolism." (PMID 33919439, 2021).
tumor (continued). "Taken together, above results demonstrated that BAP1 played tumor‐suppressive roles in PCa cell progression through inhibiting cell migration, invasion, and anchorage‐independent growth." (PMID 33155366, 2021). "SF3B1 mutations were almost always mutually exclusive of the presence of BAP1 alteration in tumor specimens except one specimen." (PMID 34830903, 2021). "Primary ccRCC tumours are characterized by genomic aberrations in the tumour suppressor gene VHL as well as variations in other driver genes such as BAP1, PBRM1, and SETD2." (PMID 34944839, 2021). "The copy number profile (normal chromosomes 3p and 8) of this tumour is correlated to a relatively good prognosis, which is supported by the positive BAP1 nuclear staining." (PMID 33588787, 2021). "Studies have shown that the auto-deubiquitination of BAP1 can counteract this process through intramolecular interactions, thereby ensuring its function in tumour suppression." (PMID 34177595, 2021). "Immunohistochemical staining of the BAP-1 protein in tumor tissue and assessment of its level of nuclear expression is a relatively quick and inexpensive alternative to genetic testing, with similar prognostic value." (PMID 33800007, 2021). "In our third patient, the primary tumor showed a combination of TSC1, CUL3, DOT1L and SETD2 gene mutations (but not BAP1), whereas the PM had the same genetic mutations plus BAP1 mutation." (PMID 34885018, 2021). "As mentioned, this finding is aligned with the fact that BAP1 is thought to function as a tumor suppressor and follow a two-hit model to result in a phenotypic change." (PMID 34830866, 2021). "Some miRNAs were increased in UM with a high HLA expression and high T cell numbers, while others were decreased, showing two opposing patterns; however, both patterns were related to the tumour’s chromosome 3/BAP1 status." (PMID 34439175, 2021). "Over expression of DLG2 isoform 7 in NB cells resulted in an increased proportion of cells in S-phase, similar to the BAP1 NB tumor suppressor." (PMID 33726762, 2021). "Apoptosis and ferroptosis mediate the tumor-suppressive function of BAP1, whereas BAP1 suppresses apoptosis to protect certain types of cancer cells." (PMID 33919439, 2021). "The proportion of BAP-1 positive cells was measured in full tumor sections, hot spots, cold spots and in scleral margins." (PMID 33800007, 2021). "Instead, previously published methods for counting the number of BAP-1 positive cells have focused on a smaller fraction of the tumor, e.g., three high power fields or similar." (PMID 33800007, 2021). "At the same time, BAP1 is downregulated by miR-125a-5p, which functions as a tumor suppresser and is abnormally expressed in breast cancer." (PMID 34575114, 2021). "To exclude this possibility, we studied the expression of merlin, BAP1, and p16Ink4a proteins, which are the three major tumor suppressors in MM cells." (PMID 34663305, 2021). "BAP1 mutations are thought to appear after the GNA11 or GNAQ mutations, correlating with a gratly increased risk for tumor progression." (PMID 33903674, 2021). "Two patients with BAP1 expression in 100% of their tumor cells were excluded from analysis, leaving 59 eligible patients." (PMID 33903674, 2021). "It has been reported that in BNC mice, where the specific disruption of the Bap1, Nf2, Cdkn2ab tumor suppressor loci in the mesothelial lining of the thoracic cavity leads to a highly aggressive MM, an infiltration of leukocytes was found." (PMID 34830817, 2021). "Taken together, BAP1 contributed to tumor suppressor by stabilizing PTEN to suppress Akt activation." (PMID 33155366, 2021). "In examining five key mutations in UM (GNAQ, GNA11, BAP1, SF3B1 and EIF1AX), the xenograft tumours matched the genomic signature of the original patient tumours in 83% of cases." (PMID 34149931, 2021).
tumor (continued). "To assess the impact of the underlying genetic mutations on the risk of metastasis, we assessed BAP1- and SF3B1-mutations in patients with available tumor tissue." (PMID 34830810, 2021). "BAP1 mutations are frequent in MPM (23–67%) and in other tumor types, including uveal melanoma (31–50%), cholangiocarcinoma (20–25%), and clear cell renal cell carcinoma (CCRCC) (8–14%)." (PMID 34597666, 2021). "Tumours with monosomy of chromosome 3 (M3), gain of 8q, a mutation in the BAP1 (BRCA1-associated protein-1) gene, or a class 2 gene expression profile are more prone to develop metastases." (PMID 34439175, 2021). "Here we describe strong H3K27me3 immunoreactivity in tumor tissue samples obtained from patients diagnosed with BAP1 wild-type MPM." (PMID 34277422, 2021). "BAP-1 expression in any tumor region added significant prognostic information to AJCC tumor size category (LRΔχ2 11.6 to 21.0, p ≤ 0.001)." (PMID 33800007, 2021). "BAP1 forms a tumor suppressor heterodimeric complex with BRCA1 and BARD1 that is involved in cell proliferation, DNA damage response, and differentiation processes through influencing chromatin remodeling." (PMID 34771666, 2021). "Collectively, these studies have shown the dichotomic functional role of BAP1 in different cancer types, as a tumor suppressor and/or tumor promoter, which further supports the notion of BAP1’s complexity." (PMID 33483476, 2021). "The C-terminally truncated ASXL1 proteins were detected in tumor cells and were sufficient to promote the deubiquitylase activity of BAP1." (PMID 32683582, 2021). "Another tumour suppressor gene-BAP1 can reduce GSH synthesis and induce ferroptosis by suppressing the level of H2A-K119ub on the SLC7A11 gene and the transcription of its mRNA, thereby inhibiting the ability of SLC7A11 to transport cysteine into the cell." (PMID 34912804, 2021). "The mean tumor volume was 913 mm3 (SD 865) and the mean number of cells measured in terms of size and BAP1 expression in each tumor was 208 403 (SD 165 587)." (PMID 33903674, 2021). "No additional mutations implicated in oncogenesis were noted from either patient’s germline or tumor sequencing, suggesting that the inactivation of BAP1 was responsible for pathogenesis." (PMID 34504799, 2021). "In a previous publication, we showed that intratumor regions with low BAP-1 expression were more likely to harbor vasculogenic mimicry, had greater microvascular density and a greater number of tumor-infiltrating macrophages." (PMID 33800007, 2021). "BAP1 is emerging as an important tumor suppressor in human cancers, which requires its deubiquitinating activity and nuclear localization." (PMID 33155366, 2021). "We stained a subset of 28 tumours with antibodies against BAP1 and MTAP (as a potential surrogate marker for CDKN2A deletion) along with PD-L1, VISTA, Ki-67 and an antibody for mitotic count." (PMID 34580349, 2021). "Robust applications of genomic analysis, such as digital PCR offering over 5000-fold coverage, are required to continue investigating the dynamic mutagenesis of BAP1 and tumor heterogeneity in UM." (PMID 33903674, 2021). "Of the patients who had a miliary metastasis pattern (n = 24), 17 had an aberrant BAP1 tumor and two had an SF3B1-mutated tumor." (PMID 34771480, 2021). "In three cases of analyzed biliary ITPNs, the complete 3p arm was lost heterozygously (88 MB), a region that contains several common tumor suppressor genes (e.g., BAP1)." (PMID 34205964, 2021). "BAP-1 measured in any tumor region added significant prognostic information to both American Joint Committee on Cancer (AJCC) tumor size category (p ≤ 0.001) and gene expression class (p ≤ 0.04)." (PMID 33800007, 2021). "The BAP1 protein has a tumor suppressor function and the presence of the BAP1 protein can be shown using immunohistochemical staining." (PMID 34771510, 2021). "To examine the effect across additional tumor types, we next knocked down BAP1 in two wt-BAP1 CCRCC cell lines." (PMID 34597666, 2021).
tumor (continued). "The tumor suppressors BAP1 and ASXL1 interact to form a polycomb deubiquitinase complex that removes monoubiquitin from histone H2A lysine 119 (H2AK119Ub)." (PMID 33802313, 2021). "As expectedly, xenografted tumor growth was markedly increased by knockdown of endogenous BAP1, which was reversely rescued by re‐expression of PTEN." (PMID 33155366, 2021). "Due to their role in homologous recombination repair, poly(ADP ribose) polymerase (PARP) inhibitors were tested for their efficacy in BAP1-null tumor cells with contrasting results." (PMID 33802313, 2021). "Consistent with previous reports, the classical driver mutations associated with ccRCC, including alterations in VHL, PBRM1, BAP1, and SETD2, were identified in tumor samples." (PMID 33806963, 2021). "When re-expressing wild-type BAP1 in M3 cell line UPMM2, we detected a substantial decrease in proliferation rate and reduced ability to form colonies, which supports the discussed role of BAP1 as a tumor suppressor." (PMID 34201614, 2021). "Overall, we report two patterns for the expression of miRNA in UM, both related to the tumour chromosome/BAP1 expression status: one showing a relation between an increase in specific miRNAs and infiltrate, the other an opposite relationship." (PMID 34439175, 2021). "When BAP1 carriers develop UM, the tumor tends to be larger in diameter, involve the ciliary body, and develop at a younger age when compared to non-BAP1 carriers." (PMID 34771666, 2021). "Of the patients who had a solitary metastasis (n = 18), 11 originated from a primary BAP1-mutated tumors and one from a primary SF3B1-mutated tumor." (PMID 34771480, 2021). "Further, we show that analysis of BAP-1 expression adds significant prognostic information to both tumor size and gene expression classifications." (PMID 33800007, 2021). "We tested the linear, logarithmic, quadratic and cubic functions’ ability to solely based on tumor volume predict manual assessments of low versus high BAP1 expression (low < 33% BAP1 positive cells, high ≥ 33%) in a model validation cohort of 40 tumors." (PMID 33903674, 2021). "This sheds light on BAP1 tumor-suppressive mechanisms and identifies new potential therapeutic strategies within PRC1 subcomplexes." (PMID 34186021, 2021). "As already observed and confirmed, expression levels of some of the HDACs were related to the tumor chromosome 3/BAP1 status." (PMID 34439300, 2021). "Those including larger numbers have used biopsies, or tissue microarrays, including tumor samples insufficient to evaluate potential intra‐tumoral heterogeneity of BAP1 staining." (PMID 32944962, 2021). "As an effective tumor suppressor gene, BRCA1-associated protein 1 (BAP1) is related to the occurrence of some malignant tumors such as UM." (PMID 34630418, 2021). "We applied our measurements of tumor cells with lost and retained BAP1 protein expression to the mean tumor from a previously published cohort of 8 033 consecutive patients." (PMID 33903674, 2021). "It should be noted that the risk of metastasis highly depends on genetic mutations (BAP1, SF3B1, and EIF1AX) in the tumor." (PMID 34830810, 2021). "Our calculations showed that the first BAP1 mutant clone of an average UM appears when the tumor is 166 days to 1665 days old, within 2 cell doublings of the first UM clone." (PMID 33903674, 2021). "The specific contribution of either maintenance of Polycomb repression or inhibition of chromatin compaction in BAP1’s tumor-suppressive role remains an open issue to be uncoupled." (PMID 34186021, 2021). "A recent genetic analysis and literature review suggested germline testing for patients with 2 more or BAP1 TPDS associated tumors, a single tumor with unusually young age at presentation, or a family history." (PMID 34504799, 2021).